PCMT1 (protein-L-isoaspartate (D-aspartate) O-methyltransferase)
Diseases named in the same sentence as PCMT1 in open-access papers (continued):
Sharing a sentence is not in itself a finding about the gene and the disease.
tumor (13 papers, 2015 to 2026). "The mechanism of radiotherapy and some anti-tumor drugs involves the activation of reactive oxygen species or DNA damage, thus PCMT1 is likely to be associated with radiotherapy resistance and drug resistance." (PMID 37596654, 2023). "The PCMT1 protein has been linked to cell anti-apoptosis and tumor metastasis, but its significance in liver hepatocellular carcinoma (LIHC) remains largely unexplored." (PMID 37596654, 2023). "Based on the Cancer Genome Atlas database, we assessed the correlation between the expression of PCMT1 and prognosis, immune invasion, and tumor mutation burden in a variety of cancers." (PMID 35535040, 2022). "PCMT1 is significantly related to the tumor mutation burden of a variety of cancers." (PMID 35535040, 2022). "Limited evidence is available about the regulation of Pcmt1 gene expression, nonetheless we identified that tumor hypoxia might contribute to its enhanced cancer-linked expression." (PMID 33198416, 2020). "In addition, we also assessed the correlation between tumor mutation burden and PCMT1 expression." (PMID 35535040, 2022). "PCMT1 overexpression in cancer cells can impairs the repair of proteins in the tumor microenvironment and hinder immune anticancer response." (PMID 39235556, 2025). "Functional experiments demonstrated that knockdown of PGK1 or PCMT1 inhibited tumor cell proliferation and reduced the phosphorylation levels of mTORC, P70S6K, S6, and AKT, indicating suppression of the PI3K/AKT/mTOR pathways." (PMID 40204712, 2025). "In univariate analysis, tumor stage, lymph-node status, and PCMT1 levels were predictive of patients survival." (PMID 39235556, 2025). "PCMT1, a member of the protein repair enzymes, participates in biological processes like apoptosis and tumor metastasis." (PMID 39238386, 2024). "In vitro and in vivo experiments were performed to assess the effect of PCMT1 on tumor cell lines and mouse tumor models, and potential pathways were explored through gene sequencing." (PMID 37596654, 2023). "This was further confirmed by caspase-3 staining, and HE staining was also performed, which showed that apoptosis of the tumor area was very obvious after knockdown of PCMT1." (PMID 37596654, 2023). "The immunofluorescence staining of tumor sections showed that the expression of CD86 was significantly increased after PCMT1 knockdown, while the expression of CD206 was decreased." (PMID 37596654, 2023). "The results showed that, compared with the control group, tumor size, weight and growth rate in the PCMT1 overexpression group were significantly increased, while those in the knockdown group were significantly decreased." (PMID 37899170, 2023). "In order to further verify the function of PCMT1 in vivo, tumor formation experiments in nude mice were conducted to prove that PCMT1 also promotes tumor growth in vivo." (PMID 37899170, 2023). "We further studied the effect of PCMT1 on tumor growth in vivo, and the results showed that the tumor growth curve was significantly slower and the tumor weight was significantly lower in the mice with PCMT1 knockdown." (PMID 37596654, 2023). "We further analyzed 50 pairs of tumor samples and corresponding adjacent normal tissues from the same patient, finding that PCMT1 expression was significantly elevated in tumor tissues." (PMID 37596654, 2023). "The modulation of PCMT1 expression appears to influence tumor progression and immune cell infiltration, suggesting a potential synergy between PCMT1-targeting strategies and immunotherapies." (PMID 37596654, 2023). "In vivo experiments showed that PCMT1 knockdown significantly reduced tumor growth rate, enhanced CD8+T cell infiltration, and increased caspase-3 expression in the tumor area." (PMID 37596654, 2023). "At present, there are relatively few studies on PCMT1 in the field of oncology, but the potential value of PCMT1 in neoplastic diseases can be found by summarizing the existing research results." (PMID 37899170, 2023).
tumor (continued). "Collectively, these in vivo observations suggested that PCMT1 is a critical factor for tumor growth, ascites formation and metastasis in EOC." (PMID 35033172, 2022). "In contrast, tumor growth and ascites formation in the PCMT1 knockout group progressed much slower than those in the control group." (PMID 35033172, 2022). "The relationship between the expressions of miR-143-3p and PCMT1 and the clinicopathological parameters of the tumor was analyzed." (PMID 33898446, 2021). "In recent years, PCMT1 has been gradually considered to be involved in tumor occurrence and development." (PMID 33898446, 2021). "We also found that PCMT1 levels increased along TNBC tumor stage." (PMID 39235556, 2025). "PCMT1 regulates tumor progression and potentially influences the activity of signaling pathways that may become therapeutic targets for the treatment of human cancers." (PMID 39235556, 2025). "Related studies have shown that PCMT1 may exist in exocrine bodies and vesicles, it may have an effect on other cells in the tumor area." (PMID 37596654, 2023). "The results revealed a significant increase in PCMT1 expression in the tumor region." (PMID 37596654, 2023). "This may be related to the promotion of M1 polarization of macrophages, thus promoting anti-tumor immunity, which may also be the possible reason for the slower tumor growth after PCMT1 knockdown." (PMID 37596654, 2023). "After further staining of tumor tissues, it was found that knockdown PCMT1 could significantly increase the apoptosis of tumor region." (PMID 37596654, 2023). "PCMT1 overexpression may be an important factor that allows tumor cells to survive longer than normal cells." (PMID 37899170, 2023). "Recent studies have revealed a substantial function for PCMT1 in tumor development and progression." (PMID 37596654, 2023). "In conclusion, overexpression of PCMT1 in PCa cells promotes tumor growth in vivo." (PMID 37899170, 2023). "Published studies on PCMT1 are mainly concentrated in non-neoplastic disease." (PMID 37899170, 2023). "Therefore, based on our results, PCMT1 is likely to inhibit tumor immunity and promote tumor progression." (PMID 37596654, 2023). "PCMT1 may be involved in the repair of damaged histones in tumor cells, thereby inhibiting tumor cell apoptosis." (PMID 37899170, 2023). "Further immune analysis demonstrated that high expression of PCMT1 could reduce tumor-killing immune cell infiltration." (PMID 37596654, 2023). "Additionally, we investigated the relationship between PCMT1 mRNA expression and various clinical variables such as tumor status, lymph node status, distant metastasis, and pathological staging." (PMID 37596654, 2023). "In addition, using the online server TIMER, we evaluated the relationship between the expression of PCMT1 and tumor immune infiltrating cell biomarkers, including B cells, CD8+ T cells, CD4+ T cells, macrophages, neutrophils, and dendritic cells." (PMID 35535040, 2022). "The results showed that PCMT1 was overexpressed in tumor tissues." (PMID 35535040, 2022). "Moreover, the tumor weight of the PCMT1 knockout group was significantly lighter than that of the control group." (PMID 35033172, 2022). "The results indicated that a high level of PCMT1 enhanced cell adhesion, suggesting that escaped cells from the initial tumor with high PCMT1 expression could quickly attach to the other site and consequently develop implantation metastasis." (PMID 35033172, 2022). "Furthermore, since PCMT1 overexpression could reduce the infiltration of tumor-killing immune cells, therapies aimed at reducing PCMT1 levels may oppose cancer immunoediting and enhance host antitumor response." (PMID 39235556, 2025). "PCMT1 expression was not related to tumor mutation burden, but immunotherapy data analysis showed that the immunotherapy effective rate might be lower in PCMT1 high expression patients." (PMID 37596654, 2023). "Therefore, PCMT1 expression is likely to affect the tumor microenvironment." (PMID 37596654, 2023).
tumor (continued). "This study aims to demonstrate the relationship between PCMT1 overexpression, TNBC pathologic malignancy features of the tumor and survival of patients." (PMID 39235556, 2025). "Comparative analysis showed that genes such as BTG3, PCMT1 and HK1 are gradually increasing in epithelial/malignant cells from tumor tissues compared to these cells from normal tissues." (PMID 39575251, 2024). "We detected the infiltration of CD4 and CD8T cells in the tumor area by flow cytometry, and the results showed that the infiltration of CD8+T cells was significantly increased after PCMT1 knockdown." (PMID 37596654, 2023). "In our study and TCGA groups, PCMT1 expression did not correlate with lymph node involvement and distant metastases but correlated with tumor stage." (PMID 39235556, 2025). "Besides, our study suggested that PCMT1 might regulate the migration, invasion and apoptosis of PCa cells by modulating the PI3K/AKT/GSK-3β signaling pathway and also can promote tumor growth in the in vivo." (PMID 37899170, 2023). "Bioinformatics immunoassay results showed that PCMT1 could affect immune infiltration in the tumor region, so we further examined the immune cell infiltration in the tumor region of mice in the two groups with or without PCMT1 knockdown." (PMID 37596654, 2023).
cancer (11 papers, 2016 to 2025). A tumor composed of atypical neoplastic, often pleomorphic cells that invade other tissues. "To determine the differences in cancer-associated gene mutations between the PCMT1 high and low-expression groups, we assessed the mutation status of representative genes in each group." (PMID 37596654, 2023). "However, PCMT1 was predominantly upregulated in cancer and PCMT1 expression was associated with higher clinical stage." (PMID 37596654, 2023). "Univariate Cox regression analysis showed that high PCMT1 expression and cancer recurrence were significant prognostic factors of shorter survival." (PMID 39235556, 2025). "The aim of the study was to demonstrate the relationship between PCMT1 protein overexpression as a prognostic indicator for patients with TNBC cancer and patient survival." (PMID 39235556, 2025). "We will also analyze the role of PCMT1 as a prognostic indicator for patients with TNBC cancer and patient survival." (PMID 39235556, 2025). "Collectively, PCMT1 plays a cancer-facilitative role in PCa by promoting the proliferation, migration and invasion of PCa cells, and inhibiting apoptosis." (PMID 37899170, 2023). "Therefore, PCMT1 may affect the mutation status of cancer-related genes." (PMID 37596654, 2023). "According to a previous study, PCMT1 is a target gene in liver cancer, indicating that it serves as a therapeutic target in multiple cancer treatments." (PMID 37953789, 2023). "PCMT1 is a protein methyltransferase enzyme that is highly expressed in multiple cancers and plays an important role in cancer development." (PMID 37953789, 2023). "We analyzed the mRNA expression of PCMT1 in 33 types of cancer, observing that its expression levels varied significantly among different cancers." (PMID 37596654, 2023). "The results of pancancer immune correlation evaluation show that, in addition to ACC, DLBC, and UVM, PCMT1 has varying degrees of correlation with the immune infiltrating cells of a variety of human cancers." (PMID 35535040, 2022). "We demonstrated that through LAMB3, PCMT1 activates integrin-FAK-Src signaling to enhance cancer cell adhesion, migration, and invasion and promote metastasis formation." (PMID 35033172, 2022). "Through systematically identifying the drivers of anoikis resistance, we uncovered the contribution of PCMT1 to focal adhesion (FA) dynamics as well as cancer metastasis." (PMID 35033172, 2022). "Pancancer analysis also revealed that the expression of PCMT1 is significantly correlated with the prognosis of a variety of cancers." (PMID 35535040, 2022). "Then, we used univariate Cox regression analysis to evaluate the prognosis of PCMT1 for a variety of human cancers." (PMID 35535040, 2022). "Pancancer analysis showed that PCMT1 is highly expressed in a variety of cancers and is significantly related to the prognosis of a variety of cancers." (PMID 35535040, 2022). "In this study, we identified PCMT1, a key enzyme in protein repair, as a critical driver of cancer anoikis resistance." (PMID 35033172, 2022). "We evaluated the correlation between TMB and PCMT1 expression in a variety of cancers, and the results showed that the expression of PCMT1 was significantly correlated with a variety of cancers, including ACC and BRCA." (PMID 35535040, 2022). "Further study will be needed to elucidate the detailed mechanism underlying PCMT1/LAMB3 interation and dissect the regulatory mechanism that drives the changes in PCMT1 levels during the process of cancer cell detachment." (PMID 35033172, 2022). "PCMT1 has a good prognostic effect on a variety of cancers, including BRCA (HR: 1.9 (1.3, 2.67), P = 0.001)." (PMID 35535040, 2022). "Protein-L-isoaspartate (D-aspartate) O-methyltransferase (PCMT1) is involved in the occurrence and development of a variety of malignant tumors." (PMID 35535040, 2022). "PCMT1 overexpression may lead to uncontrolled cell proliferation, disruption of apoptosis and cancer cell migration during TNBC development." (PMID 39235556, 2025).
cancer (continued). "PCMT1 has been proven to participate in the regulation of the proliferation, apoptosis, and migration of different cancer cells, which further promotes the occurrence and development of cancers." (PMID 37953789, 2023). "We conducted a pan-cancer analysis to examine the expression differences of PCMT1." (PMID 37596654, 2023). "In vitro experiments indicated that PCMT1 knockdown could inhibit cancer cell proliferation and migration while promoting apoptosis." (PMID 37596654, 2023). "PCMT1 may regulate cancer-related processes such as apoptosis through regulating multiple proteins such as Mst1." (PMID 37953789, 2023). "Considering our finding that extracellular PCMT1 plays roles in cancer cell invasiveness, we evaluated whether secreted PCMT1 affects the FAK-Src pathway." (PMID 35033172, 2022). "This suggested that PCMT1 could promote cancer cell spreading to other organs through blood vessels." (PMID 35033172, 2022). "More importantly, since the antibody blocking PCMT1 significantly inhibited cancer cell migration and invasion, this finding may provide a novel strategy for therapeutic intervention of metastatic ovarian cancer with PCMT1-targeting antibodies or inhibitors." (PMID 35033172, 2022). "PCMT1 may regulate these RBPs to influence the AS of cancer-related genes." (PMID 37953789, 2023). "Importantly, we first linked PCMT1 with the ECM protein LAMB3 and demonstrated that the PCMT1-LAMB3 interaction activates the integrin-FAK-Src pathway to promote cancer cell adhesion, migration and invasion and that these effects can be reversed by treatment with a PCMT1-blocking antibody." (PMID 35033172, 2022). "In conclusion, our study identified the molecular targets of PCMT1 in the TNBC cell line, expands our understanding of the regulatory mechanisms of PCMT1 in cancer progression, and provides novel insights into the progression of TNBC." (PMID 37953789, 2023). "Extracellular matrix (ECM) protein LAMB3 can interact with PCMT1 to activate the integrin-FAK-Src pathway that promotes the adhesion, invasion, and migration of cancer cells." (PMID 37953789, 2023). "Therefore, comprehensive analysis of the global change in the deamidation/isomerization status of all proteins, especially in the extracellular space during cancer metastasis, by proteomics analysis may help us to better understand the role of PCMT1 in promoting this process." (PMID 35033172, 2022). "In a comparison of the control with cancer group (grade 4), the 5-marker panel (CCT3, PCMT1, TKT, TOMM34, UBA1) showed better sensitivity (0.90 and 0.90), specificity (0.93 and 1.00), error rate (8 and 4%), and AUC value (0.94 and 0.96) than the best single marker (TOMM34)." (PMID 37875819, 2023). "However, the precise role of PCMT1 in cancer development and progression has not been elucidated." (PMID 35033172, 2022). "However, the exact role of PCMT1 in cancer progression is not clear." (PMID 35033172, 2022).
neurodegenerative disease (1 paper, 2024). A disorder of the central nervous system characterized by gradual and progressive loss of neural tissue and neurologic function. "PCMT1 downregulation is linked to neurodegenerative diseases and may increase ß-amyloid production." (PMID 38760690, 2024).
PCMT1 also shares sentences with these, for which no sentence is quoted: neurological diseases (2 papers); Alzheimer disease (1); bone metastasis (1); colon adenocarcinoma (1); diffuse large B-cell lymphoma (1); Down syndrome (1); endometrial cancer (1); gynecological cancer (1); infection (1); lymphoid neoplasm (1); metastasis (1); multiple sclerosis (1); preeclampsia (1); soft tissue sarcoma (1); spina bifida (1); thrombosis (1); uveal melanoma (1).